NR2F2-AS1 (NR2F2 antisense RNA 1)
Gene: Long non-coding RNA gene on chromosome 15 (96,080,713 to 96,337,579, reverse strand). Ensembl gene ENSG00000247809.
Diseases named in the same sentence as NR2F2-AS1 in open-access papers:
NR2F2-AS1 is named in the same sentence as 2 diseases in open-access papers, as found by Europe PMC text mining. Sharing a sentence is not in itself a finding about the gene and the disease. The quoted sentences say what the papers report.
cervical cancer (1 paper, 2020). A primary or metastatic malignant neoplasm involving the cervix. "Although some studies have confirmed that lncRNA NR2F2 antisense RNA 1 (NR2F2-AS1) is a pro-cancer gene in many cancers, the molecular mechanism of NR2F2-AS1 in cervical cancer has not been completely elucidated." (PMID 32469064, 2020).
cancer (1 paper, 2020). A tumor composed of atypical neoplastic, often pleomorphic cells that invade other tissues. "There is proof that as a member of lncRNAs, NR2F2 antisense RNA 1 (NR2F2-AS1) acts as a tumor promoter in some cancers." (PMID 32469064, 2020).